FUT1 (fucosyltransferase 1 (H blood group))
Diseases named in the same sentence as FUT1 in open-access papers (continued):
Sharing a sentence is not in itself a finding about the gene and the disease.
cancer (40 papers, 2011 to 2026). A tumor composed of atypical neoplastic, often pleomorphic cells that invade other tissues. "Further evaluation of the diagnostic value of FUT1 in pan-cancer revealed that in diagnostic ROC models for READ and COAD, the area under the curve (AUC) reached 0.999 and 0.985, respectively." (PMID 40084262, 2025). "In certain cancers, MS.275 was suggested to reverse molecular characteristics caused by dysregulated FUT1 expression, potentially mitigating its pro-tumorigenic effects." (PMID 40084262, 2025). "Analysis of OS, DSS, PFI, and DFI across pan-cancer types revealed that high FUT1 expression is a risk factor for poor survival prognosis in certain cancers." (PMID 40084262, 2025). "This indicates that FUT1-mediated glycosylation is intricately linked with sialylation processes, suggesting a potential mechanistic connection between FUT1, sialylation, and cancer progression." (PMID 40084262, 2025). "The ROC curves indicated that FUT1 can serve as a diagnostic biomarker for certain cancers." (PMID 40084262, 2025). "The α-1,2-fucosyltransferase, FUT1, plays a central role in blood type determination, the establishment of the gut microbiota, and cancer progression." (PMID 42225237, 2026). "Together, these results identify miRNAs as key regulators of FUT1 and demonstrate that bidirectional miRNA control of glycosyltransferases can reshape cell-surface glycosylation with important implications for cancer biology." (PMID 42225237, 2026). "To assess potential genomic alterations of FUT1 in specific cancers, we performed a pan-cancer analysis of FUT1 copy number variations (CNVs) and genomic instability-related scores." (PMID 40084262, 2025). "In this study, FUT1 expression was systematically analyzed across 33 cancer types using data from multiple public databases, including CCLE, TCGA, and GTEx." (PMID 40084262, 2025). "RNA expression profiles of 1,019 cancer cell lines were retrieved from the CCLE database to analyze FUT1 expression across cancers." (PMID 40084262, 2025). "The results indicated that FUT1 expression was negatively correlated with StromalScore and ImmuneScore in most cancers, but showed strong positive correlations in UVM, SKCM, SARC, and PCPG." (PMID 40084262, 2025). "Next, we analyzed FUT1 mRNA expression across various human cancer types using TCGA data and compared it to corresponding normal tissues from the GTEx database." (PMID 40084262, 2025). "The results indicated a positive correlation between the expression levels of key RNA modification genes and FUT1 expression in most cancers, with a particularly strong positive correlation observed in OV." (PMID 40084262, 2025). "Despite these insights, most studies on FUT1 have focused on single cancer types, leaving its broader role across the pan-cancer spectrum and its potential connection to immune-related features underexplored." (PMID 40084262, 2025). "FUT1 expression was found to vary across cancers, correlating with poor prognosis in ACC, BLCA, and COAD and demonstrating high diagnostic accuracy in READ and COAD." (PMID 40084262, 2025). "This study highlights FUT1 as a promising pan-cancer therapeutic target and prognostic biomarker, offering valuable insights into cancer treatment strategies." (PMID 40084262, 2025). "In some cancers, FUT1 was also expressed in immune cell populations, with monocyte and macrophage subsets showing higher expression compared to other immune cell types." (PMID 40084262, 2025). "The results indicated that FUT1 was predominantly expressed in endothelial cells across most cancers." (PMID 40084262, 2025). "To investigate FUT1 mRNA expression at the single-cell level, we analyzed pan-cancer single-cell RNA-seq data from TISCH." (PMID 40084262, 2025). "Kaplan-Meier survival curves showed that higher FUT1 expression correlated with lower OS probability in nine cancer types." (PMID 40084262, 2025).
cancer (continued). "Annotation of FUT1 methylation probes revealed that in most cancers, the methylation levels of DNA promoters and enhancers were negatively correlated with mRNA levels, such as in BRCA (ρ=-0.49, p =1.87e-48)." (PMID 40084262, 2025). "In summary, our results shed light on the multifaceted role of FUT1 in cancer progression and immunity, providing a foundation for developing targeted therapies and improving cancer treatment strategies." (PMID 40084262, 2025). "The results showed that FUT1 mRNA expression was significantly higher in many cancers compared to their normal counterparts." (PMID 40084262, 2025). "FUT1 was upregulated in 14 cancers and downregulated in 11, consistent with findings in liver, kidney, ovarian, colorectal, breast, prostate, and lung cancers." (PMID 40084262, 2025). "The construction of a protein-protein interaction (PPI) network provides further insights into the biological functions of FUT1 in pan-cancer." (PMID 40084262, 2025). "Treatment of cancer cells with a KDM6B inhibitor downregulated FUT1 (Fucosyltransferase 1) gene, which is also related to metastasis." (PMID 36233212, 2022). "The regulation of genes encoding key glycosyltransferases that allow a switch from the a-series to the b-series gangliosides, as well as FUT1 and FUT2 regulation, is a major element to understand the specific cancer-associated ganglioside expression." (PMID 34200284, 2021). "We knocked down FUT1 by short interfering RNA (siRNA) in four HER2-overexpressing human cancer cell lines, including NCI-N87, MKN7, SKBr3 and BT474." (PMID 23128605, 2013). "Further studies are necessary to identify a biomarker to predict which HER2-positive cancer cells are sensitive to FUT1 inhibition." (PMID 23128605, 2013). "The results showed that in 22 cancer types, FUT1 DNA methylation patterns were complex." (PMID 40084262, 2025). "Our results revealed a strong positive correlation between high FUT1 expression and metastasis scores across pan-cancer types (R=0.5, p < 2.2e-16), as well as positive correlations with scores for other pathways, including quiescence, invasion, and epithelial-mesenchymal transition (EMT)." (PMID 40084262, 2025). "Notably, FUT1 was highly expressed in BLCA and UCEC, marking the first report of its association with poor prognosis in these cancers." (PMID 40084262, 2025). "Notably, somatic copy number alterations of FUT10 were highly correlated with FUT1 mRNA expression in most cancers." (PMID 40084262, 2025). "Studies have shown that FUT1 knockdowns are linked to decreased cell proliferation, tumorigenicity, and migration in several cancer cell lines or keratinocyte cell lines, whereas overexpression of FUT1 enhanced tumorigenesis and migration in different cancer cell lines." (PMID 39420441, 2024). "In other words, cancer types exhibiting higher FUT methylation are more sensitive to targeted therapies with the exception of FUT1 and FUT6, suggesting that cancer cells can inhibit fucosylation upon increased methylation of FUT promoter are more susceptible to therapy." (PMID 36961502, 2023). "Our findings are consistent with previous reports that FUT1 increased alpha 1, 2-fucose of cell surface to promote tumorigenesis and metastasis in colon cancer, and that FUT1 served as a promoter for cancer progression in ovarian, hepatocellular, and oral cancer." (PMID 30854233, 2019). "More importantly, this finding may yield a strong scientific rationale for the future development of FUT1 inhibitor for cancer therapy." (PMID 27560716, 2016). "FUT1 also modulates cell proliferation in the HER2-positive cancer cell line NCI-N87." (PMID 26161361, 2015). "Fut1 is overexpressed in some cancers such as colon and pancreas." (PMID 24467809, 2014). "Fut1 mRNA in cancer tissues was elevated compared to normal tissues." (PMID 24467809, 2014). "FUT1 may serve as a new molecular target for HER2-overexpressing human cancers with activated EGFR signaling." (PMID 23128605, 2013).
cancer (continued). "Correlation analysis of FUT1 expression with immune-related functional gene sets, including immune checkpoint genes, immunostimulators, immunoinhibitors, chemokines, and chemokine receptors, showed significant positive correlations in cancers such as UVM, PCPG, KIRP, and LIHC." (PMID 40084262, 2025). "Thus, FUT1 may serve as a new molecular target for HER2-overexpressing human cancers with activated EGFR signaling." (PMID 26161361, 2015). "We selected three cancer cell lines from distinct cancer types—UMUC3, MDA-MB-361 and HCT116—to perform basic experiments validating the specific biological functions of FUT1 in BLCA, BRCA, and COAD." (PMID 40084262, 2025). "Other studies demonstrated that the knockdown of FUT1 reduces EGFR signaling, probably mediated by downregulation of A and/or Lewis Y antigen, making the cancer cells more sensitive to EGFR deprivation." (PMID 39420441, 2024). "In light of the impact of FUT1 and FUT2 on cancer stem cells (CSC) and cell metastasis, we investigated the role of FUT1 and FUT2 in epithelial-mesenchymal transition (EMT), which was considered a hallmark of CSC and metastasis." (PMID 30854233, 2019). "To date, FUT1 and its glycan products are relatively better studied than FUT2 in relation to cancers." (PMID 30854233, 2019). "FUT1 also correlated with immune-related markers, including TMB and MSI, in several cancers." (PMID 40084262, 2025). "Exploring the mechanisms through which FUT1 influences drug sensitivity could lead to more personalized and effective treatment strategies, especially for patients with EGFR-mutant cancers." (PMID 40084262, 2025). "Further analysis of immune cell infiltration in the TME revealed that FUT1 expression was generally negatively correlated with T cell infiltration across most cancers, although the differences were not statistically significant." (PMID 40084262, 2025). "Moreover, high FUT1 expression had a significant impact on estrogen response, KRAS signaling, and TNF-α signaling via NF-κB pathways in most cancer types." (PMID 40084262, 2025). "Alpha1,2-fucosyltransferases, FUT1 and FUT2, which transfer fucoses onto the terminal galactose of N-acetyl-lactosamine via α1,2-linkage have been shown to be highly expressed in various types of cancers." (PMID 27560716, 2016). "Furthermore, an FUT1- and FUT2-overexpressing cell line proliferates more aggressively than the parent cell line, suggesting that activation of EGFR and HER2 induces a malignant phenotype in human cancer cells." (PMID 23128605, 2013). "Furthermore, understanding how FUT1-mediated glycosylation impacts cancer therapy may reveal novel avenues for improving treatment outcomes and overcoming resistance to current therapies." (PMID 40084262, 2025).
bacterial infection (1 paper, 2016). "For Meishan pigs, no suitable genetic markers, including the FUT1 gene, could be applied to screen F18-resistance and -sensitive individuals, so the current study attempted to use piglets to conduct the bacterial infection experiment." (PMID 27809935, 2016).
FUT1 also shares sentences with these, for which no sentence is quoted: viral infection (5 papers); colitis (4); autoimmune disease (3); gastric cancer (3); glioblastoma (3); inflammatory bowel disease (3); leukemia (3); lupus (3); measles (3); asthma (2); graft versus host disease (2); histoplasmosis (2); lung diseases (2); metastatic melanoma (2); mycosis (2); non-small cell lung carcinoma (2); Oral Squamous Cell Carcinoma (2); sarcoma (2); typhoid fever (2); adenocarcinoma (1); alcohol (1); anthrax (1); astrocytomas (1); autoimmune gastritis (1); autoimmune peripheral neuropathy (1); autoimmune thyroiditis (1); bacteremia (1); bladder tumors (1); brain tumor (1); cardiomyopathy (1).
A further 53 diseases each share a sentence with FUT1 in 1 paper.